NLRP3 (NLR family pyrin domain containing 3)
Diseases named in the same sentence as NLRP3 in open-access papers (continued):
Sharing a sentence is not in itself a finding about the gene and the disease.
infection (continued). "In that study, the NLRP3 inflammasome was activated by S. suis leading to production of IL-1β, resulting in CRS, further highlighting that the inflammasome is a contributor to the effects of CRS following infections." (PMID 33149733, 2020). "To further clarify the role of the Nlrp3 inflammasome activation in developing STSS caused by SS2, we infected three genotypes of mice [WT mice, Nlrp3−/− mice, and WT mice injected with the Nlrp3 inhibitor (MCC950) prior to infection] with a high dose of 2 × 109 CFU SS2." (PMID 32922370, 2020). "Nevertheless, the control of the parasite burden during the chronic stage of the infection in the brain did not require NLRP3, ASC, or Casp1/11." (PMID 31194844, 2019). "Moreover, the expression levels of NLRP3, NLRP12 and IFI-16 was sustained longer (i.e., until 24 h) in THP-1 cells after infection with the virulent strains." (PMID 31367214, 2019). "As a consequence, the absence of ASC or Casp1/11, but not NLRP3, also resulted in elevated T. gondii dissemination during the acute stage of infection, as indicated by an increased pathogen burden in the liver and spleen of the infected mice." (PMID 31194844, 2019). "In addition, we measured the CFUs after 8 h of infection and found that the CFU in NLRP3-knockout and wild-type cells were 116 ± 5 and 58 ± 7, respectively." (PMID 31417575, 2019). "In addition, the increased expressions of NLRP3, ASC and pro‐caspase‐1 after infection with E. coli or S. aureus was obstructed in the presence of BAY 11‐7082." (PMID 30362186, 2019). "Similarly, T. gondii infected Nlrp3-/-, Asc-/-, and Casp1/11-/- mice demonstrated modest reductions of IFN-γ within the sera on day 8 post-infection." (PMID 31194844, 2019). "Infection with VSV or EMCV likely triggers a form of necrosis (plasma membrane rupture) as a consequence of the lytic cell death, promoting the efflux of intracellular K+, a necessary and sufficient upstream signaling event in NLRP3 activation." (PMID 31024004, 2019). "While MNV-induced diarrheic responses were not affected, Stat1-/- mice additionally lacking either Nlrp3 or GSDMD displayed lower levels of the fecal inflammatory marker Lipocalin-2 as well as delayed lethality after gastrointestinal MNV infection." (PMID 31017981, 2019). "During the infection of human macrophages by Mycobacterium tuberculosis, SPB independently regulates C-C motif chemokine ligand (CCL) secretion and multiple genes within the NLRP3 inflammasome pathway." (PMID 30469547, 2018). "Moreover, some NOD-like receptors, such as NOD-like receptor family pyrin domain containing 3 (NLRP3, also known as cryopyrin) and NLR apoptosis inhibitory protein 5, have been observed to be activated upon cellular infection with IAV." (PMID 29556226, 2018). "Unlike Ifnar1-/- mice, Caspase1-/- and Nlrp3-/- mice were not protected from IOE infection, thus we sought to further address a potential role for necroptotic cell death in driving HSPC loss during IOE infection." (PMID 30080899, 2018). "Moreover, baicalin is reported to inhibit NOD-like receptor (NLR) family, pyrin containing domain 3 (NLRP3) inflammasome activation partly through augmenting PKA signaling, and improve survival in an animal infection model using Escherichia coli." (PMID 29360768, 2018). "Indeed, infection with B. abortus triggers the production of mtROS in BMDM after 17 h and contributes to the secretion of IL-1β in an NLRP3-dependent manner." (PMID 29581535, 2018). "In the BPG treatment subgroup, NLRP3 mRNA expression was suppressed at 18 d post-infection (4 d after the first BPG treatment) and returned to “normal” levels [(i.e., not significantly different from the blank group (P > 0.05)] at 42 d post-infection." (PMID 29490620, 2018). "In the infected rabbit group, the NLRP3 mRNA levels showed a trend in elevation to decline and reached a peak at 18 d post-infection in the BPG treatment subgroup and at 21 d in the no BPG treatment subgroup." (PMID 29490620, 2018).
infection (continued). "The effect was further enhanced by infection, compared to the scrambled siRNA control or non-transfected cells (P < 0.01 for NLRP3- or ASC-siRNA transfected cells, respectively)." (PMID 30030504, 2018). "Data from our previously published studies suggest that multiple inflammasome complexes including NLRP3, AIM2, and NLRC4 are upregulated during infection with virulent Ehrlichia and may play a role in the development of Ehrlichia-induced liver injury." (PMID 29049365, 2017). "In the present study, proteomic and transcriptional analyses did not reveal induction of NLRP3 and IL-1β expression after infection of guinea pigs with H5N1 virus." (PMID 28418930, 2017). "Gram-negative bacteria, including Escherichia coli and Citrobacter rodentium, introduce LPS into the host cytoplasm during infection and engage non-canonical activation of the NLRP3 inflammasome via caspase-1116." (PMID 28345580, 2017). "To define the inflammasome complexes that contribute to IL-1β secretion following infection with virulent IOE and regulated by MyD88, we further analyzed mRNA expression of several inflammasome complexes (NLRP3, NLRC4, AIM2) in the liver tissues of WT and MyD88-/- mice on day 7 p.i with IOE." (PMID 29049365, 2017). "Overall, these data suggest that an additional LPS priming does not enhance NLRP3 activation in monocytes, in response to S. typhimurium after overnight incubation, with infection alone sufficient to induce priming and secretion of IL-1." (PMID 28761045, 2017). "We therefore investigated whether Syk signaling was required for NLRP3 inflammasome-dependent caspase-1 activation and IL-1β production following SEA infection." (PMID 28808303, 2017). "Therefore, the expression of IL-1β, IL-18, NLRP3, Caspase-1, ASC, and Syk mRNA was characterized in lung macerates of WT, Nlrp3−/−, Casp1/11−/−, and Asc−/− mice at week 4 after infection." (PMID 28740491, 2017). "It has also been reported that infection with RNA virus initiates assembly of the RIP1–RIP3 complex, which promotes activation of the GTPase DRP1 and its translocation to mitochondria to drive mitochondrial damage and activation of the NLRP3 inflammasome." (PMID 27652274, 2016). "We did not observe inflammasome focus formation in Nlrp3 -/- BMDMs upon infection with stationary phase S. typhimurium." (PMID 27011353, 2016). "Unlike Nlrp3-deficient mice, Aim2-/-, Caspase-1/11-/-, Asc-/-, and IL-1R-/- mice died within 8–11 dpi after lethal Ft LVS infection or between 6 and 7 dpi after SchuS4." (PMID 27926940, 2016). "The amounts of secreted IL-1ß induced by B. infantis and B. fragilis were significantly less than the amount induced by infection with Citrobacter rodentium, a Gram-negative bacterial enteropathogen that is known to activate the NLRP3 inflammasome." (PMID 27505062, 2016). "Recently, a non-canonical NLRP3 inflammasome has also been described during infection by enteric pathogens." (PMID 27617233, 2016). "Nec-1s treatment does not result in an increase in lung neutrophils following Ft LVS infection, while macrophage numbers are higher at days 3 and 6 post-infection, suggesting that the early neutrophil response is restricted by Nlrp3, but not by RIPK1." (PMID 27926940, 2016). "To determine whether NLRP3, ASC and Caspase-1 are activated in peripheral blood monocytes following infection by H. parasuis, we evaluated the expression of NLRP3, ASC and caspase-1 at mRNA levels by qRT-PCR." (PMID 27502767, 2016). "Nlrp3−/− animals also showed enhanced lung barrier leakage (but not increased bacterial loads or altered cytokine production) after infection with a different pneumococcal strain (serotype 2 strain D39) in comparison to WT mice." (PMID 27476670, 2016). "Two inflammasome complexes, NLRP3 and NLRC4, are required to fully combat infection." (PMID 27011353, 2016).
infection (continued). "Unlike the WT cell line, an immortalized BMDM line derived from NLRP3 KO mice did not secrete IL-1ß in response to infection with live B. infantis or B. fragilis, indicating the involvement of the NLRP3 inflammasome." (PMID 27505062, 2016). "For example, IL-1 is a well-established driver of hematopoesis in response to infection or myelosupression, but potential roles for NLRP3 in steady-state or emergency hematopoesis have not yet been explored in detail." (PMID 27551512, 2016). "For the first time, temporal use of the specific NLRP3 inhibitor MCC950 has identified that the NLRP3 inflammasome mediates both an early protective immune response, and later in infection, induces a highly inflammatory, damaging state that contributes to disease pathogenesis." (PMID 27283237, 2016). "Infection with Salmonella enterica serovar Typhimurium (S. Typhimurium) triggers the formation of a complex inflammasome that can include NLRC4, NLR family PYRIN domain-containing protein 3 (NLRP3), ASC, caspase-1 and caspase-8 (refs 5, 17, 18, 19)." (PMID 27670879, 2016). "Regarding cryptococcosis, regardless of the route of infection (e.g., intraperitoneal or intranasal), mice lacking NLRP3 or ASC presented poorer survival compared with wildtype mice." (PMID 26204108, 2015). "Collectively, we here provide evidence that Leishmania major and mexicana parasites are able to dampen IL-1β secretion during initial stages of infection, rendering cells non-responsive towards stimulation of the NLRP3 inflammasome." (PMID 26114647, 2015). "Therefore, it is possible that the NLRP3 inflammasome is activated through ROS and ox-LDL produced due to infection, as well as through direct inflammasome activation due to infection by periodontal bacteria." (PMID 26783845, 2015). "We therefore examined gene expression for several important interferon-related genes (IFNα2, IFNα4, IFNβ, IFNαβR, IFNγ, IFNγR, Irf3, Irf7, Mx1, Oas1, IFITM1, IFITM2), along with inflammasome-related genes IL-1β and NLRP3, and chemokines CCL5, CCL7, and CCL12 at d1 post-infection." (PMID 26110868, 2015). "Interestingly, A. fumigatus induces cooperative and synergistic activation of the NLRP3 and AIM2 inflammasomes in dendritic cells and in a mouse intranasal infection model." (PMID 26204108, 2015). "Activation of NLRP3 has also been shown in response to A. fumigatus in vitro, but a functional role in infection has not been demonstrated." (PMID 25375146, 2014). "Nlrp3−/− mice, however, expressed equal plasma levels of IL-18 after infection at all time points when compared to WT mice, indicating that IL-18 production is independent of NLRP3 during experimental S. Typhimurium infection in vivo." (PMID 25115174, 2014). "Previously, we have shown that infection with C. rodentium specifically activates the non-canonical NLRP3 inflammasome." (PMID 25254654, 2014). "Next, we semi-quantitatively scored for the extent of inflammation histological samples of liver and spleen obtained 2 and 5 days after infection to further evaluate the role of ASC and NLRP3 in systemic in vivo host defense against S. Typhimurium in the typhoid model." (PMID 25115174, 2014). "Our collective findings from the infection with WT bacteria suggest that NLRP3, but not NLRC4, plays a major role in inducing caspase-1 activation." (PMID 23357873, 2013). "In contrast, infection of primed NLRP3−/− cells with X31 showed no significant IL-1β production compared to the medium control, showing the NLP3-dependence of influenza virus-induced IL-1β production." (PMID 23737748, 2013). "For example, a recent study showed a role for NLRP12 in inflammasome formation and IL-1β/IL-18 maturation in response to a subcutaneous infection with a genetically attenuated strain of Yersinia, but not other activators that engage the NLRP3 inflammasome." (PMID 23577168, 2013).
infection (continued). "Interestingly, in human lung tissue not only macrophages in the alveolar air space were positive to staining, but expression of NLRP3 was also seen in bronchial epithelial cells and alveolar type II cells (ATII) showing intensification after NTHi infection." (PMID 23840534, 2013). "Cillóniz and coworkers demonstrated robust transcriptional changes of inflammatory response genes, including upregulation of inflammasome genes (e.g., CASP1, IL1B, and NLRP3), in response to H5N1 VN1203 compared to 1918 pandemic influenza virus at day 1 post-infection." (PMID 23895213, 2013). "Macrophages isolated from the NLRP3−/− and caspase-1−/− mice failed to kill amastigotes and exhibited an infection index that was even higher than that observed in MyD88−/− macrophages." (PMID 24098823, 2013). "In these cells, the NLRC4 inflammasome is activated upon infection with Salmonella, whereas the activation of NLRP3 inflammasome is not triggered by the NLRP3 stimulators such as ATP." (PMID 23357873, 2013). "It has been shown that infection by M. tuberculosis and M. marinum may induce ESX-1-dependent NLRP3 inflammasome activation." (PMID 22558425, 2012). "Upon infection with EMCV, NLRP3 was redistributed to the perinuclear region or cytoplasmic granular structures, which is also observed in cells stimulated with other NLRP3 ligands such as monosodium urate (MSU), alum or nigericin and considered as a hallmark of NLRP3 activation." (PMID 22916014, 2012). "We now show that, in addition to the NLRP3 inflammasome, a different inflammasome containing NLRC4 is also important in protecting against infection with Candida albicans, and appears to be functioning in the mucosal lining of the mouth and intestines, rather than in immune cells." (PMID 22174673, 2011). "NLRP3 is important in inflammasome activation in response to ATP and a number of other diverse stimuli, but not in response to infection with P. aeruginosa." (PMID 20955240, 2011). "At 16 weeks post-infection, Pycard−/− and Nlrp3−/− animals produced comparable if not enhanced levels of cleaved IL-1β compared to wild type mice." (PMID 20808838, 2010). "NOD-like receptor family pyrin domain containing 3 (NLRP3) is a cytoplasmic pattern-recognition receptor (PRR), and the nucleotide-binding domain of the leucine-rich repeat family of NLRP3 inflammatory vesicles is required for the host immune system to defend against external infection." (PMID 41491143, 2026). "These discrepancies, i.e., activation or not of NLRC4 along with NLRP3, could be attributed to differences in the infection models, fungal strains, and microbiota composition." (PMID 41249509, 2025). "The study also suggests a role for fetal infection in regulating the activity of the NLRP3 inflammasome in utero and the important developmental mechanisms regulating IL-1β responses early in gestation, in part due to a downregulation of TLR-mediated NLRP3 expression." (PMID 41149694, 2025). "However, NLRP3 inhibitor (MCC950 sodium) treatment improved cellviability, reduced CASP1 activity, and attenuated IL-1β cytokineproduction during infection, suggesting that NLRP3 inhibitors may be a promisingtherapy against pyroptotic inflammation." (PMID 41114588, 2025). "The protein domains of mammals and fish NLRP3 are compared and found that there is a FISNA domain present mostly in fish NLRPs and a B30.2 (PRY-SPRY) domain unique in fish NLRs, which may play key roles in the anti-infection immunity of fish." (PMID 41200183, 2025). "Similarly, expression of GBP1, NLRP3, and IL1B was downregulated in both HIF1‐KD and GBP1‐KD macrophages, while expression of ASC1 and HIF1A was upregulated in HIF1‐KD and GBP1‐KD macrophages, respectively, upon H37Rv infection, compared with controls." (PMID 41287823, 2025).
infection (continued). "The common pathways upregulated upon infection by each of these three viruses included innate antiviral and inflammatory pathways, such as OAS and ISG15-mediated antiviral responses, interferon α/β signaling, cytokine and interleukin signaling, NOD1/2 signaling, and the NLRP3 inflammasome pathway." (PMID 40857262, 2025). "Baicalin alleviates NOD-like receptor pyrin 3 inflammasome (NLRP3) and NF-κB signaling in piglet mononuclear phagocytes during GPS infection and inhibits the release of high mobility group box 1 (HMGB1) protein in peripheral blood monocytes induced by GPS infection." (PMID 40867785, 2025). "The NLRP3 and IL-1β genes, which are involved in pyroptosis, a type of cell death mediated by inflammasome activation, were significantly upregulated in J774A.1 cells following infections with all strains compared to non-infected controls (p < 0.05)." (PMID 40727705, 2025). "The binding of NUR77 and NLRP3 was not affected during the infection of P. aeruginosa." (PMID 39998486, 2025). "To determine whether infection with A. actinomycetemcomitans activates non-canonical NLRP3-mediated inflammasomes, we examined BMDMs from caspase-11-deficient mice." (PMID 39143049, 2024). "In RVFV infected Nlrp3-/- mouse, the virus titre was comparable with that from infected WT mouse at an early time point (2 days post-infection), indicating that the activated NLRP3 pyroptosis did not control viral replication but mainly contributed to inflammatory pathogenesis." (PMID 39213434, 2024). "Upon activation by NLRP3 inflammasome, Caspase-1 can cleave Gasdermin D (GSDMD) to form GSDMD-N, which bounds to phosphatidylinositol phosphates and phosphatidylserine presented in the inner leaflet of cell membrane, and induces the pyroptosis during the intracellular infection by S. aureus." (PMID 38515339, 2024). "However, primary human macrophages infected with T. gondii do not produce IL-1β, possibly because of the downregulation of NLRP3 during monocyte-to-macrophage differentiation and the lack of induction during infection." (PMID 39548522, 2024). "However, infection of Nlrp3-/- mice showed no phenotypes, with similar lesion development and parasite load compared to control C57BL/6 mice." (PMID 39250503, 2024). "Interestingly, NLRP3−/− mice showed mostly PDL1 single positive macrophages and a significantly reduced population of PDL1+ PDL2+ peritoneal macrophages (~ 7% from F480+ cells) at 4 weeks of infection." (PMID 38842647, 2024). "The NLRP3 and IL1-β genes which are associated with pyroptosis, i.e., cell death mediated by the formation of the inflammasome, were overexpressed in J774A.1 cells in response to all infections when compared with the non-infected cells (p < 0.05)." (PMID 38721607, 2024). "In this study, we show that prion-infected cells were relatively highly resistant to infection with a neurotropic influenza A virus strain A/WSN/33 (H1N1) (hereafter referred to as IAV/WSN), suppressing IAV/WSN-induced necroptosis, by activating NLRP3 inflammasome." (PMID 39194237, 2024). "However, specific data on increased infection rates in patients treated with NLRP3 inhibitors are not yet available." (PMID 39188718, 2024). "At 8 weeks of infection, NLRP3−/− mice exhibited a nearly absent population of these macrophages." (PMID 38842647, 2024). "Since a number of vector-borne viruses target monocyte/macrophage cells in the peripheral blood for infection, whether the BAK-dependent NLRP3 activation represents a common inflammatory pathogenesis mechanism triggered by these viruses could be investigated in the future." (PMID 39213434, 2024). "Like other chronic age-related diseases, individuals with kidney disease have an accelerated ageing phenotype caused by convergence of fundamental mechanisms that underlie age-related tissue dysfunction, including chronic “sterile” (absence of infection) NLRP3-induced inflammation." (PMID 38970061, 2024).